UPK3BL1 (uroplakin 3B like 1)
Synonyms: UPLP; UPK3BL
Tractability: Antibody: UniProt predicts a signal peptide or a membrane-spanning region. PROTAC: ubiquitination databases record sites on it.
Gene: Protein-coding gene on chromosome 7 (102,637,025 to 102,642,856, reverse strand). Ensembl gene ENSG00000267368.
Subcellular location: Membrane
Gene Ontology:
Cellular component: membrane
Genetic constraint (gnomAD): Loss-of-function variants: 0 observed, 2.27 expected, observed/expected ratio (o/e) 0, 90% interval 0 to 1.24. That is too few expected variants to judge how well the gene tolerates losing a copy. Missense variants: 0 observed, 17.83 expected, observed/expected ratio (o/e) 0, 90% interval 0 to 0.17. Synonymous variants: 1 observed, 6.18 expected, observed/expected ratio (o/e) 0.16, 90% interval 0.057 to 0.77.
Homologues: Orthologues: macaque UPK3BL2 (93% identical), dog UPK3BL2 (66% identical), mouse Upk3bl (61% identical), rat Upk3bl1 (59% identical), tropical clawed frog upk3b (29% identical), zebrafish upk3b (22% identical). Paralogues in human: UPK3BL2 (100% identical), UPK3B (38% identical), UPK3A (22% identical).
Diseases named in the same sentence as UPK3BL1 in open-access papers:
UPK3BL1 is named in the same sentence as 5 diseases in open-access papers, as found by Europe PMC text mining. Sharing a sentence is not in itself a finding about the gene and the disease. The quoted sentences say what the papers report.
breast carcinoma (1 paper, 2025). "Together, ZNF32 H179A and H183A promote the proliferation of breast cancer cells by differentially upregulating ISY1-RAB43 and UPK3BL1 as well as downregulating SNX22 expressions." (PMID 40046230, 2025).
UPK3BL1 also shares sentences with these, for which no sentence is quoted: glioblastoma (1 paper); Hypertension (1); Insulin resistance (1); mesothelioma (1).